MAP6D1 (MAP6 domain containing 1)
Description:
May have microtubule-stabilizing activity.
Synonyms: SL21; FLJ12748; MAPO6D1
Tractability: No criterion of Open Targets' tractability assessment is met for any kind of drug.
Gene: Protein-coding gene on chromosome 3 (183,815,884 to 183,825,594, reverse strand). Ensembl gene ENSG00000180834.
Subcellular location: Golgi apparatus; Cytoplasm, cytoskeleton
Subcellular location (Human Protein Atlas): Cytosol
Gene Ontology:
Molecular function: microtubule binding; calmodulin binding
Biological process: cytoskeleton-dependent intracellular transport; regulation of microtubule cytoskeleton organization; microtubule cytoskeleton organization
Cellular component: cis-Golgi network; Golgi-associated vesicle; microtubule; cytoskeleton; Golgi apparatus
Genetic constraint (gnomAD): Loss-of-function variants: 14 observed, 11.84 expected, observed/expected ratio (o/e) 1.18, 90% interval 0.78 to 1.77. The synonymous counts are far from expectation, so gnomAD's model fits this gene poorly and the ratio says little. Missense variants: 313 observed, 194.23 expected, observed/expected ratio (o/e) 1.61, 90% interval 1.47 to 1.77. Synonymous variants: 141 observed, 88.95 expected, observed/expected ratio (o/e) 1.59, 90% interval 1.38 to 1.82.
Homologues: Orthologues: chimpanzee MAP6D1 (98% identical), dog MAP6D1 (81% identical), rabbit MAP6D1 (81% identical), pig MAP6D1 (79% identical), mouse Map6d1 (71% identical), rat Map6d1 (70% identical), guinea pig MAP6D1 (68% identical), zebrafish map6d1 (35% identical). Paralogues in human: MAP6 (38% identical).
Diseases named in the same sentence as MAP6D1 in open-access papers:
MAP6D1 is named in the same sentence as 5 diseases in open-access papers, as found by Europe PMC text mining. Sharing a sentence is not in itself a finding about the gene and the disease. The quoted sentences say what the papers report.
ciliopathies (1 paper, 2025). "In neurons, MAP6d1 localises to the proximal part of primary cilia via its Mn-motif, with its loss resulting in shortened cilia, a characteristic of ciliopathies." (PMID 40617876, 2025).
Cirrhosis (1 paper, 2012). A chronic disorder of the liver in which liver tissue becomes scarred and is partially replaced by regenerative nodules and fibrotic tissue resulting in loss of liver function. "Most cell structure related genes were up-regulated in initial fibrosis (HYLS1, MAP6D1 and TOR1AIP1) and genes related to cell adhesion, cell cycle and signaling showed differential expression in both initial fibrosis and cirrhosis." (PMID 22397681, 2012).
tumour (1 paper, 2025). "Eight genes (CDH23, HARS2, LLGL2, LTBP1, MAP6D1, MIPOL1, SCYL3, ZNF418) showed some degree of promoter methylation in at least one tumour, but only MIPOL1 exhibited probable homozygous methylation in more than one sample." (PMID 39794353, 2025).
MAP6D1 also shares sentences with these, for which no sentence is quoted: fibrosis (1 paper); ovarian carcinoma (1).